TGFB2 (transforming growth factor beta 2)
Diseases named in the same sentence as TGFB2 in open-access papers (continued):
Sharing a sentence is not in itself a finding about the gene and the disease.
melanoma (continued). "JQ1 was characterized by induction of inhibitory relationship linking regulators of inflammation (IFNG, IL17A, TGFB2), melanoma biological behavior (EGFR, WNT3A, TEADs, MRTFB), cell-cell interaction (CD44, CCN2), YAP pathway (LLGL2, NSUN6) and main transcriptional regulators (FOS, JUN, FOXM1)." (PMID 36397155, 2022). "In addition, TGFβ2, a member of the TGFβ cytokine family, plays an important role for BM establishment as demonstrated in a metastasis mouse model, where melanoma cell lines expressing high levels of TGFβ2 grew only in the brain parenchyma." (PMID 35884845, 2022). "The difference in location of a metastatic tumor was likely due to the expression of transforming growth factor-beta 2 (TGF-β2) in melanoma cells: TGF-β2 mRNA was highly expressed by the K-1735 cells, whereas the B16 cells or B16 x K-1735 cell mixes had low expression." (PMID 32194848, 2020). "We elucidated whether the level of SOX10 in melanoma cells changed by treatment with TGFβ2 and concomitantly led to expression of CD133." (PMID 24799129, 2014). "We suggest that TGFβ2 produced by primary melanoma may convert peripheral DCs into tolerogenic cells." (PMID 17565341, 2007). "Our finding supports the hypothesis that the presence of TGFβ2 is correlated with melanoma progression." (PMID 17565341, 2007). "In primary melanoma, TGFβ2 is likely to render peripheral DCs tolerogenic, while in lymph nodes IDO and TGFβ1 may have a major effect." (PMID 17565341, 2007). "This suggests that TGFβ2 (produced either directly by melanoma or by associated fibroblasts) and not TGFβ1 might in fact be the primary melanoma-derived immunosuppressive factor." (PMID 17565341, 2007). "In contrast to the positive prognostic impact of these genes in combination with TGFB2, NLE1 is elevated and positively correlated with tumor stage and metastasis in melanoma." (PMID 41373732, 2025). "Subsequently, we screened a set of melanoma-related target genes with TCF12 binding sites by RT-qPCR and verified that TCF12 knockdown significantly decreased Tgfb2 transcription, leading to reduced protein expression." (PMID 37760480, 2023). "We found that, despite the fact that depletion of TGFB2 on its own did not alter melanoma proliferation, it was able to block the growth advantage conferred by TCF12 overexpression." (PMID 37760480, 2023). "As reported in the literature, the mRNA transcript for TGFβ-2 is characteristic only for melanoma cells, while the transcripts for TGFβ-1 and TGFβ-3 - for normal and neoplastic cells." (PMID 36899279, 2023). "In the Liver-HCC, Breast-AdenoCA, Skin-Melanoma, and Lung-AdenoCA samples, the TGFB2 copy number was specifically increased, rather than the ploidy level, in almost all tumors." (PMID 34344966, 2021). "We have analyzed the changes in PAX3d, MITF-m and TGFB2 copy numbers on a larger CMM patients’ cohort (with or without melanoma relapse) during their clinical monitoring." (PMID 29156734, 2017). "In contrast, the much lower expression of TGFβ2 is more closely related to the presence of melanoma cells, and this cytokine is nearly absent in negative SLN." (PMID 17565341, 2007). "Notably, only a fraction of melanoma patients displays signs of TGFB2 reduction, hinting that its presence is not a primary event in melanoma development but rather associated with tumor progression." (PMID 37760480, 2023). "Once the melanoma actually metastasises, and the SLN becomes positive, TGFβ2 produced by invasive melanoma cells may further increase the immunosuppression, resulting in the development or attraction of suppressor/regulatory T cells, which in turn release immunosuppressive cytokines." (PMID 17565341, 2007). "No significant decrease was observed in patients with melanoma recurrence (p = 0.197 for MITF-m; p = 0.325 for TGFB2)." (PMID 29156734, 2017).
ocular hypertension (36 papers, 2012 to 2026). Abnormally high intraocular pressure. "TGFβ2 has also been shown to cause ocular hypertension both in vivo and ex vivo and is elevated in POAG patients." (PMID 39829808, 2025). "In anterior segment perfusion organ culture models the addition of TGFβ2 elevates IOP and overexpression of TGFβ2 in mouse eyes causes ocular hypertension." (PMID 35912101, 2022). "In the present study, we found that AS.IV treatment lowered TGFβ2 induced ocular hypertension in mice and is further associated with decreased ECM deposition and ER stress in the TM." (PMID 34830390, 2021). "Mutation in EDA−/− also blocked TGFβ2-induced ocular hypertension compared with C57BL/6J controls and uninjected control eyes." (PMID 32555351, 2020). "In addition, we also tested the role of NF-κB, an upstream regulator of Bambi expression, in TGFβ2-induced ocular hypertension and found that mutation in the p50 subunit of NF-κB prevented TGFβ2-induced ocular hypertension." (PMID 35912101, 2022). "Interestingly, the topical ocular AS.IV eye drops (1 mM) significantly decreased TGFβ2 induced ocular hypertension in mice, and this was associated with a decrease in FN, Col-1 (ECM), KDEL (ER stress) and αSMA in mouse TM tissues." (PMID 34830390, 2021). "We also demonstrated that mutation in Tlr4 blocked TGFβ2-induced ocular hypertension in mice." (PMID 32555351, 2020). "Recently, a CRISPR interference system has been utilised to selectively deacetylate histones in the TGFβ2 gene promoter, reducing TGFβ2 expression in human TM cells and ameliorating ocular hypertension in a TGFβ2-overexpressing mouse model." (PMID 39516652, 2025). "ATG4B deficiency also prevented the development of glaucomatous IOP elevation in the experimental TGFβ2 ocular hypertensive model." (PMID 37620383, 2023). "Here we have investigated the effect of autophagy deficiency on IOP elevation and RGC degeneration in two different mouse models of glaucomatous chronic IOP elevation: DBA/2J and TGFβ2-induced ocular hypertensive mouse models." (PMID 37620383, 2023). "Mice harboring both the constitutively active EDA isoform and knock out alleles of TLR4 (B6.EDA+/+TLR4−/− mice) exhibited normal IOP and were resistant to TGFβ2-induced ocular hypertension." (PMID 35619185, 2022). "We have previously shown that TGFβ2-induced ocular hypertension is dependent on both FN-EDA and its receptor toll-like receptor 4 (TLR4)." (PMID 35619185, 2022). "By utilizing our TGFβ2-induced ocular hypertension model, we have identified toll-like receptor 4 (TLR4) signaling as a novel molecular pathway involved in the development and progression of glaucomatous TM damage." (PMID 35216043, 2022). "Previously, we utilized several transgenic mouse strains to determine that both TLR4 and the EDA isoform of FN are necessary for TGFβ2-induced ocular hypertension." (PMID 35619185, 2022). "We demonstrated that conditional knock-out of Bambi in the TM resulted in increased ECM deposition and development of ocular hypertension, likely due to uninhibited TGFβ2 signaling." (PMID 35912101, 2022). "For ocular hypertension to occur in mice, TGFβ2 signaling through the canonical SMAD pathway is essential." (PMID 35912101, 2022). "Our study demonstrates that LV-mediated gene transfer is an effective tool for investigating TGFβ2-induced ocular hypertension in mice." (PMID 35805889, 2022). "Taken together, this indicates that the effects of TGFβ2 signaling are a major component in the development of ocular hypertension and that TGFβ2 regulates the expression of ECM proteins in the TM." (PMID 35912101, 2022). "TGFβ2 also induces ocular hypertension (OHT) in perfusion cultured human eyes as well as in in vivo mouse eyes." (PMID 34499703, 2021). "Taken together, the results suggest that AS.IV prevents TGFβ2 induced ocular hypertension by modulating ECM deposition and ER stress in the TM." (PMID 34830390, 2021).
ocular hypertension (continued). "In this study we used an inhibitory peptide called FUD that specifically prevents fibronectin fibrillogenesis to explore the role of fibronectin fibrils in TGFβ2-induced ocular hypertension." (PMID 32822410, 2020). "Using a fibronectin-binding peptide called FUD that can disrupt fibronectin fibrillogenesis, we examined if disrupting fibronectin fibrillogenesis would affect IOP in the TGFβ2 BALB/cJ mouse model of ocular hypertension." (PMID 32822410, 2020). "Here, e.g., the extra domain A of fibronectin was recently described to elevate IOP through TLR4 signaling in a TGFβ2-induced ocular hypertension mouse model." (PMID 33162981, 2020). "Next, since ocular hypertensive phenotypes are typically multifactorial, we investigated the effect of the interaction between GIMs and exogenous TGFβ2 on this pathway." (PMID 32973273, 2020). "We investigated the role of an endogenous Toll-like receptor 4 (TLR4) ligand, fibronectin-EDA (FN-EDA), in TGFβ2-induced ocular hypertension in mice." (PMID 32555351, 2020). "TGFβ2 signaling is well-established in ocular hypertension partly because of its potent regulatory role on TM ECM restructuring." (PMID 32973273, 2020). "Ad5.TGFβ2 induced ocular hypertension in wildtype C57BL/6J mice and further amplified the IOP in constitutively active EDA mice." (PMID 32555351, 2020). "As expected, C57BL/6J mice eyes injected with Ad5.TGFβ2 developed ocular hypertension compared to their contralateral uninjected eye15,51." (PMID 32555351, 2020). "In conclusion, we have demonstrated that both Tlr4 and FN-EDA are necessary for TGFβ2-induced ocular hypertension." (PMID 32555351, 2020). "Given the relevance of Smad-dependent TGFβ2 pathways in ocular hypertension and glaucoma, we performed Western blotting to investigate the expression of total and phosphorylated Smad2 and Smad3 molecules." (PMID 32973273, 2020). "We also identified that TGFβ2-induced ocular hypertension is dependent on both EDA and TLR4." (PMID 35619185, 2022). "The TM from POAG eyes is stiffer than that from healthy eyes; transforming growth factor beta 2 (TGFβ2), the predominant TGFβ isoform in the eye and aqueous humor, has been identified as a major contributor to the pathologic changes occurring in ocular hypertension and POAG." (PMID 35300422, 2022). "TGFβ2 levels are known to be elevated in the aqueous humor of POAG patients and increased expression of TGFβ2 causes an elevation in IOP in rodent models of ocular hypertension." (PMID 34440692, 2021). "Next, we examined whether topical ocular AS.IV eye drops lower IOP in a mouse model of TGFβ2 induced ocular hypertension." (PMID 34830390, 2021). "Interestingly the TM of B6.EDA−/− mice appears to develop normally as shown by gross clinical and histological analysis, and these mice are completely resistant to TGFβ2 induced ocular hypertension." (PMID 32555351, 2020). "We utilized transgenic mouse strains that either constitutively express only FN containing the EDA isoform or contain an EDA-null allele and express only FN lacking EDA, with or without a mutation in Tlr4, in our inducible mouse model of ocular hypertension by injection of Ad5.TGFβ2." (PMID 32555351, 2020). "In order to determine whether FN-EDA and TLR4 are necessary for Ad5.TGFβ2-induced ocular hypertension phenotype, we tested wildtype C57BL/6J (n = 17), B6.TLR4−/− mice (n = 8), B6.EDA+/+ mice, B6.EDA−/− (n = 18), B6.EDA−/− /TLR4−/− (n = 23) and B6.EDA+/+/ TLR4−/− (n = 16) mice in our model system." (PMID 32555351, 2020). "We further expanded on this hypothesis here and demonstrated that exclusion of the EDA exon in B6.EDA−/− mice blocked TGFβ2 induced ocular hypertension and constitutive inclusion of the EDA exon in B6.EDA +/+ caused ocular hypertension and further exacerbated the effect of TGFβ2." (PMID 32555351, 2020).
ocular hypertension (continued). "The contribution of common genetic variation at the FOXC1, TGFβ2, and BMP4 loci to risk of POAG was investigated in a case-control association study in 330 British Caucasian individuals comprised of 272 high-tension glaucoma (HTG) and 58 ocular hypertension (OHT), and 276 matched controls." (PMID 22736943, 2012). "Our group has shown that there is crosstalk between the TGFβ2 and TLR4 signaling pathways in the TM and that this crosstalk is contributing to glaucomatous ocular hypertension." (PMID 35912101, 2022). "Inconsistent with the previous report, TGFβ2 treatment significantly enhanced NF-kB activation in the TM cells and is necessary for TGFβ2 induced ECM production and ocular hypertension." (PMID 34830390, 2021). "We found that CTSK expression is tightly regulated by mechanical stress, as well as in response to ocular hypertension inducing factors, including DEX, TGFβ2, Endo-1, and CTGF." (PMID 34831087, 2021). "The activation of NF-κB signaling plays an important role in TGFβ2 induced ECM production and ocular hypertension." (PMID 34830390, 2021). "TGFβ2 has also been shown to mediate fibrosis development and ECM deposition within the TM, and induce ocular hypertension in both mice and in ex vivo perfusion organ culture systems." (PMID 32555351, 2020). "NF-κB is necessary for TGFβ2-induced ECM production and ocular hypertension." (PMID 35216043, 2022). "Although our analysis of TGFβ2 in AH and at the iridocorneal angle were not statistically significant, separate analysis of ocular hypertensive eyes demonstrated that active TGFβ2 levels were significantly elevated in AH (by 4.78-fold) and in anterior segments (by 93.96%) of LV_TGFβ2-treated eyes." (PMID 35805889, 2022). "Alternatively, a feed-forward relationship between ocular hypertension and TGFβ2 production may exist, as indicated by positive, though not significant, correlations in the POAG and CACG groups, such that a high IOP could augment AH level of TGFβ2." (PMID 31382918, 2019).
prostate carcinoma (33 papers, 2015 to 2025). A carcinoma that arises from epithelial cells of the prostate gland. "In prostate cancer, a quantitative increase in promoter methylation levels of TGFβ2 are associated with PCa progression." (PMID 34136553, 2021). "Recently, the TGFβ2/GAS6-Axl axis was shown to be necessary for the induction of dormancy of prostate cancer cells in the BM." (PMID 33987095, 2021). "We also found that relative to normal tissue controls, TGFβ2 expression was lower in brain, breast, renal, lung and prostate cancer tissues." (PMID 32530106, 2020). "Moreover, murine models of metastatic prostate cancer have shown osteoblast secreted TGFb2 and GDF10 are key to promoting cellular quiescence and maintaining tumour dormancy in the bone." (PMID 37608096, 2023). "Oncomine data revealed elevated TGFβ2 levels in brain, breast, colorectal, oesophageal, gastric, head and neck, renal, liver, pancreatic and lymphoma cancers relative to normal tissue, whereas in certain data sets TGFβ2 levels were lower in brain, breast, kidney, lung and prostate cancer." (PMID 32530106, 2020). "However, different prostate cancer cell lines had distinct responses to TGFβ2." (PMID 33391538, 2021). "In this study, we identified several genes including the cytokines Il-6, Tgfb2, Cxcl1, and Ctgf, metallopeptidases Mmp13, Adamts1, Adamts4, and Adamts5, and transcription factors Junb, Fos, Stat3 and Cebpb that were up-regulated in osteoblasts as a result of prostate cancer–osteoblast interactions." (PMID 27600237, 2015). "An integrated network of Tgfb2, Il-6, Cxcl1, and Ctgf interactions revealed several putative binding partners in osteoblasts and/or prostate cancer and suggested that these secreted cytokines may control up-regulated transcription factors Junb, Cebpb and Stat3 in osteoblasts." (PMID 27600237, 2015). "BMPs are a diverse class of growth factor proteins that belong to the transforming growth factor-β (TGFB1, TGFB2, TGFBR1, TGFBR2) superfamily, and aberrant expression of various BMPs has been reported in several tumor tissues, including prostate cancer." (PMID 40596459, 2025). "Bone secretes factors such as TGFβ2, GDF10, and others, which induce cellular quiescence and dormancy in some prostate cancer cell lines." (PMID 37464317, 2023). "Both TGFb2 and GDF10 ligands bind TGFb3R to increase nuclear translocation of (active) phospho-p38, which deepens quiescence in prostate cancer cells by promoting expression of the CKI p27." (PMID 37608096, 2023). "TGFβ2 is a BM-derived factor shown previously to impose dormancy in HNSCC and in prostate cancer cells." (PMID 33987095, 2021). "In prostate cancer, it has been demonstrated that GAS6/AXL and transforming growth factor-beta 2 (TGF-β2) signaling regulates tumor cell dormancy." (PMID 31694201, 2019). "TGFβ2 and GDF10 can promote cell cycle arrest by binding to the TGF-βRIII receptor expressed by prostate cancer cells." (PMID 31817646, 2019). "Differentiated osteoblasts located around the tumor cells in the bone induced dormancy in prostate cancer cells by secreting proteins including growth differentiation factor 10 (GDF10) and TGFβ2." (PMID 31817646, 2019). "TGFβ1 did not promote dormancy in prostate cancer cells, whereas TGFβ2 induced quiescence in C4-2B4 cells." (PMID 33391538, 2021). "Genes, such as CHAF1B, INHBA, TGFB2, SKA3, and HELLS, are responsible for the invasion of various cancer cells, such as hepatocellular carcinoma, gastric cancer cells, renal cell carcinoma, prostate cancer, head and neck cancer, but these genes may be involved in the invasion of BRCA cells." (PMID 31311202, 2019).
liver fibrosis (29 papers, 2010 to 2025). "Our study, however, reveals that BTC inhibition by DHA simultaneously disrupts the integrin pathway in macrophages and TGFβ‐2‐driven collagen production by hepatic stellate cells, two processes that synergize in the development of liver fibrosis." (PMID 37859621, 2023). "Of note, we found that at MH stage, loss of FOXA2 led to a significant increase in the expression of mRNA levels of genes associated with hepatic fibrosis and HSC activation, such as PDGF, MMP2, TGFβ2, TGFβ3, TGFβR2, and DLK1 among others." (PMID 35973994, 2022). "CDH11 is linked to fibrotic diseases such as liver fibrosis, scleroderma, and pulmonary fibrosis, and CDH11 is up-regulated by TGFβ2." (PMID 35573666, 2022). "The inhibition of TGFβ1 and TGFβ2 expression and activation has been demonstrated to attenuate liver fibrosis, including biliary fibrosis." (PMID 21209952, 2010). "TGFβ1 and TGFβ2 are key cytokines in the development of liver fibrosis that can be expressed in a variety of cells including activated stellate cells, myofibroblats, macrophages and activated cholangiocytes." (PMID 21209952, 2010). "Indeed, we revealed that BTC induces the TGFβ‐2, a critical contributor to liver fibrosis via collagen production by hepatic stellate cells." (PMID 37859621, 2023). "A recent study demonstrated that TGFβ‐2, but not TGFβ‐1 has a critical non‐redundant role in promoting lung and liver fibrosis." (PMID 37859621, 2023). "For example, miR-20a-5p was downregulated during liver fibrosis and transfection of miR-20a-5p reduced the production of the proinflammatory cytokines IL-6, TNF-α, IL-18, and IFN-γ in a murine hepatoma cell line by targeting transforming growth factor beta 2 (TGFB2)." (PMID 36634655, 2023). "Upregulation of TGFB1, TGFB2, COL1A1, and COL3A1 were found at W14 post-infection but in both infected and uninfected groups, suggesting that there may be alternative mechanisms for hepatic fibrosis in liver fluke-infected cattle." (PMID 31555289, 2019).